DOT1L (DOT1 like histone lysine methyltransferase)
Diseases named in the same sentence as DOT1L in open-access papers (continued):
Sharing a sentence is not in itself a finding about the gene and the disease.
colon carcinoma (9 papers, 2016 to 2023). "DOT1L involvement in the regulation of the antitumor immune response was described in pancreatic and colon cancers." (PMID 35495127, 2022). "MiR-133b targets DOT1L, a histone H3 lysine-79 specific N-methyltransferase upregulated in colon cancer cells-derived spheroids, reducing CSC phenotype, and improving sensitivity to 5-FU and L-OHP." (PMID 33429840, 2021). "We detected DOT1L protein levels in different cell lines originating from normal colon or colon cancer tissues at different stages according to the Duke's staging system and found a strong correlation between DOT1L levels and tumor cell stages." (PMID 32042335, 2020). "In a recent study on pancreatic cancer and colon cancer, DOT1L is shown to epigenetically activated FOXM1, which inhibits maturation phenotypes and function of bone marrow–derived dendritic cells through the Wnt5a signaling pathway." (PMID 31888761, 2019). "With bioinformatics analysis, we suggested that DOT1L‐induced H3K79me2 is associated with FOXM1 regulation in pancreatic cancer and colon cancer." (PMID 30628173, 2019). "Then we analyzed the correlation of DOT1L expression and the prognosis of patients with colon cancers by using Kaplan-Meier (KM) analysis." (PMID 31888761, 2019). "Taken together, these data suggested that DOT1L‐induced H3K79me2 was associated with the regulation of FOXM1 in pancreatic cancer and colon cancer." (PMID 30628173, 2019). "Colon cancer in Black people seemed to have a higher DOT1L expression than other races including White and Yellow people." (PMID 31888761, 2019). "DOT1L was highly expressed in colon cancers with responder to FOLFOX6 (leucovorin, fluorouracil, oxaliplatin) treatment, compared with that without responder to FOLFOX6 treatment." (PMID 31888761, 2019). "In colon cancer, DOT1L increases cancer stemness and tumorigenic potential by inducing the core stem cell genes NANOG, SOX2 and Pou5F1." (PMID 27581651, 2016). "Similarly, CBP can promote tumor cell metastasis by catalyzing the acetylation of the DOT1L protein in colon cancer cells to improve their protein stability." (PMID 37103124, 2023). "Interestingly, DOT1L preferred to be highly expressed in colon cancer from male patients than that of the female patients." (PMID 31888761, 2019). "Furthermore, DOT1L expression was shown to be highly expressed in grade III colon cancer, compared to that of the grade II colon cancer." (PMID 31888761, 2019). "Moreover, DOT1L expression was correlated with metastasis of colon cancers according to the analysis in several clinical datasheets." (PMID 31888761, 2019). "Interestingly, DOT1L was highly expressed in colon cancers with these characteristics." (PMID 31888761, 2019). "In human colon cancer cells, CBP can mediate the acetylation of K358 of DOT1L, which is positively correlated with the staging of colon cancer." (PMID 36359005, 2022). "We found that only the expression of disruptor of telomeric silencing 1‐like (DOT1L), the sole enzyme that specificity mediates H3K79 methylation, correlated with FOXM1 in both pancreatic cancer and colon cancer tissue." (PMID 30628173, 2019). "Since histone methylation is modified by the histone methyltransferase, we next examined the clinical relevance of histone methyltransferase (MLL1, MLL2, MLL3, MLL4, SET1A, SET1B for H3K4me3 and DOT1L for H3K79me2) and FOXM1 in pancreatic cancer and colon cancer." (PMID 30628173, 2019). "However, in this study, we found that DOT1L, the only identified H3K79 methyltransferase, was highly expressed in CRC tissues and correlated well with the prognosis of patients with colon cancers." (PMID 31888761, 2019).
colon carcinoma (continued). "Specifically, DOT1L levels were undetectable in normal human CCD841 cells, and increased from the low malignant colon cancer SW480 and SW116 cell lines (Duke's A stage) to the highly malignant colon cancer HCT116, LoVo, DLD-1 and HT-29 cell lines (Duke's B and C stages)." (PMID 32042335, 2020).
neuroblastoma (9 papers, 2019 to 2024). Neuroblastoma (NB) is the most common solid, extracranial childhood tumor. "Recently, high DOT1L expression in neuroblastoma tissues was associated with poor prognosis, but this was not investigated further so its significance remains unclear." (PMID 35495127, 2022). "In mice xenografts of neuroblastoma cells stably expressing doxycycline-inducible DOT1L shRNA, ablating DOT1L expression with doxycycline significantly reduced ODC1 and E2F2 expression, reduced tumor progression, and improved overall survival." (PMID 38807594, 2024). "Prognostic and therapeutic consequences of DOT1L overexpression within ovary 47 as well as malignancies of the colon 48, breast 49, 50 and neuroblastoma 51 are known." (PMID 38495505, 2024). "As a starting point to investigate NPM1/DOT1L synergy in mouse cells, we used reciprocal co-IP followed by immunoblot analysis and detected endogenous NPM1 interacting with DOT1L in neuroblastoma N2a cells." (PMID 37759327, 2023). "In this work, we addressed a potential synergy between mouse NPM1 and DOT1L, with a specific focus on heterochromatin organization around nucleoli in the neuroblastoma N2a cell line." (PMID 37759327, 2023). "For example, DOT1L promotes the progression of neuroblastoma, whereas it protects against the development of UV-induced melanoma." (PMID 31908356, 2020). "Our data show that NPM1 interacts with DOT1L in the neuroblastoma N2a cell line." (PMID 37759327, 2023). "Finally, DOT1L expression has been correlated with poor patient survival also in human neuroblastoma, a finding confirmed also in mice xenografts, where DOT1L ablation significantly reduced neuroblastoma tumor growth and improved OS." (PMID 35495127, 2022). "In addition, in line with the association between DOT1L and MYC, an elegant study demonstrated that this lysine methyltransferase is involved in neuroblastoma oncogenesis, and its mRNA and protein expression upregulated by N-Myc." (PMID 35495127, 2022). "Silencing DOT1L decreased the expression of OCD1 and E2F2 (two target genes of N‐Myc) and suppressed the growth of neuroblastoma cells." (PMID 39307938, 2024). "Besides, DOT1L is a novel co-factor in N-Myc-mediated transcriptional activation of target genes and neuroblastoma oncogenesis, and DOT1L inhibitors may be a clinical medication to treat N-Myc-amplified neuroblastoma." (PMID 31888761, 2019). "Moreover, high EZH2 or DOT1L expression had prognostic significance independent of MYCN amplification status, age of diagnosis and International Neuroblastoma Staging System (INSS) disease stage." (PMID 39501501, 2024).
anemia (8 papers, 2020 to 2025). A reduction in the number of red blood cells, the amount of hemoglobin, and/or the volume of packed red blood cells. "DOT1L is critical for normal hematopoiesis, with Dot1l-deficient mice displaying severe anemia and death at E10.5-13.5." (PMID 36497471, 2022). "We detected that DOT1L deficiency results in lethal anemia in Dot1l knockout (Dot1l-KO) mouse embryos starting at embryonic day 11.5 (E11.5) and they failed to thrive beyond E13.5." (PMID 35111761, 2021). "However, loss of DOT1L in young mice (3–6 weeks) resulted in anemia, neutropenia, lymphopenia, and reduced BM cellularity with significant reductions in HSPC compartments." (PMID 35712672, 2022). "We observed that loss of DOT1L in mice (Dot1L-KO) results in lethal anemia during mid-gestation." (PMID 35401699, 2022). "Loss of DOT1L in knockout (Dot1l-KO) mouse embryos resulted in lethal anemia at midgestational age." (PMID 35111761, 2021). "Loss of DOT1L protein led to lethal anemia in the knockout embryos." (PMID 35111761, 2021). "Thus, a reduced level of TRPC6 expression due to the loss of DOT1L in erythroid progenitor cells may result in lethal anemia despite normal EPO signaling." (PMID 35563527, 2022). "DOT1L has been proved to play an important role in embryonic development as embryos with DOT1L deletion exhibit severe anemia and perish before E13.5." (PMID 40214280, 2025). "We observed that Dot1L-KO embryos develop more slowly than WT embryos and suffer from lethal anemia." (PMID 35401699, 2022). "The Dot1l conditioned knockout mice showed a phenotypic decrease in the number of bone marrow small cells and HSPCs chambers, therefore the Dot1l deletion resulted in severe anemia in internal organs such as the liver." (PMID 40214280, 2025). "One study noticed anemia and bleeding in multiple organs upon Dot1l deletion." (PMID 35712672, 2022). "Total DOT1L-KO is likely lethal from severe anemia, and therefore blood differentiation could be particularly sensitive to loss of H3K79me2, or the requirement for DOT1L may be revealed first in this early differentiating population." (PMID 35733849, 2022). "Similar to DOT1L KO mice, DOT1L-MM embryos died before E13.5, but showed no anemia or defective angiogenesis in the yolk sac or the aorta-gonad-mesonephros region." (PMID 35712672, 2022). "We previously reported that Dot1l knockout (Dot1lKO) HPCs in the yolk sac failed to develop properly, which resulted in lethal anemia." (PMID 35563527, 2022). "However, when examined at E10.5, Dot1l-MM embryos did not exhibit overt anemia like the Dot1l-KO." (PMID 35111761, 2021).
gastric cancer (8 papers, 2021 to 2024). A primary or metastatic malignant neoplasm involving the stomach. "In this study, carried out in a small cohort of patients with hereditary gastric cancer identified, a DOT1L variant (p.Pro1146Leu) was identified by exome sequencing, among other candidate susceptibility genes, in affected individuals but not in control cases." (PMID 35495127, 2022). "DOT1L is found significantly increased in gastric malignant tumors and regulates cyclin-dependent kinase (CDK) 4 and 6, which accelerate the proliferation of the gastric tumors." (PMID 34500733, 2021). "Interestingly hesperetin, a citrus flavanone present in citrus fruits, exhibited anti-tumorigenic effects in gastric cancer by reducing DOT1L stability and abundance, therefore affecting H3K79 methylation and the expression of cancer genes." (PMID 35495127, 2022). "Similarly, DOT1L is overexpressed and plays important role in gastric cancer, triple-negative breast cancer, and clear-cell renal carcinoma." (PMID 34253709, 2021). "High DOT1L expression has been found in a number of nonhematologic neoplasms including breast, prostate, ovarian, gastric cancer, and other malignancies." (PMID 35495127, 2022).
multiple myeloma (8 papers, 2016 to 2025). "For instance, we previously showed that DOT1L inhibition suppresses proliferation of multiple myeloma cells by downregulating MYC-IRF4 signaling." (PMID 41299712, 2025). "DOT1 Like Histone Lysine Methyltransferase (DOT1L), which catalyzes methylation of histone H3 lysine 79, has been reported to be required for myeloma cell survival through enhancing IRF4-Myc signaling." (PMID 35338347, 2023). "Further experiments showed that the use of DOT1L inhibitors in multiple myeloma can induce cell cycle arrest and apoptosis, and can strongly inhibit cell proliferation in vitro." (PMID 34149432, 2021). "DOT1L was also shown to be essential for the growth and viability of a subset of multiple myeloma cell lines along with the SETDB1 protein." (PMID 34500733, 2021). "The inhibition of DOT1L was able to block the proliferation of myeloma cells in in vitro models." (PMID 34439223, 2021). "Serendipitous observations during high-throughput drug screens indicated that the use of DOT1L inhibitors might be expandable to multiple myeloma (MM)." (PMID 32215184, 2020). "Actually, a recent study also reported that DOT1L could transcriptionally activate c-Myc expression in multiple myeloma." (PMID 31888761, 2019). "Recently, we reported that DOT1L inhibition induces DNA damage and activates IFN signaling in multiple myeloma (MM) cells." (PMID 41299712, 2025). "DOT1L, a methyltransferase responsible for the methylation of H3K79, was also found to be crucial for the survival of myeloma cells." (PMID 34439223, 2021). "Higher expression levels of DOT1L were detected, especially in the early stages of multiple myeloma, MGUS and smoldering multiple myeloma (SMM)." (PMID 34439223, 2021).
lymphoma (6 papers, 2014 to 2026). A malignant (clonal) proliferation of B- lymphocytes or T- lymphocytes which involves the lymph nodes, bone marrow and/or extranodal sites. "Our findings in murine lymphoma add to a growing list of cancers that rely on DOT1L activity, and therefore underline the importance of understanding the regulation of DOT1L." (PMID 31304633, 2019). "Given the important roles of HDAC and DOT1L in lymphocytes it would certainly be interesting the assess the effect of HDAC inhibitors in combination with DOT1L inhibitors on normal immune cells and in other types of lymphoma." (PMID 36425063, 2022). "To date, this is the first report to reveal the oncogenic role of DOT1L in lymphoma." (PMID 39307938, 2024). "We summarize the current state of development for inhibitors against Menin‐KMT2A, DOT1L, KDM1A, and Polycomb complexes, and the arginine methyltransferase PRMT5 for the treatment of myeloid malignancies, lymphoma, and different solid tumors." (PMID 40181550, 2026). "Thymic lymphomas that arise upon genetic deletion of Hdac1 retained the increased H3K79 methylation and were sensitive to reduced DOT1L dosage." (PMID 31304633, 2019).
renal fibrosis (6 papers, 2017 to 2026). A final common manifestation of a wide variety of chronic kidney diseases characterized by glomerulosclerosis and tubulointerstitial fibrosis. "These divergent findings highlight the complex and multifaceted nature of DOT1L’s functions and suggest that its modulation of different targets and pathways may lead to different outcomes in renal fibrosis." (PMID 38929505, 2024). "In contrast, in UUO models, blocking DOT1L with EPZ5676 alleviates renal fibrosis by inhibiting multiple fibrosis pathways (including Smad3, EGFR, PDGFR and NF-κB pathway), up-regulating the expressions of renal protective factors such as PTEN, Klotho and Smad7,2." (PMID 35559246, 2022). "In IR-induced AKI models, blocking DOT1L with EPZ004777 could alleviate renal fibrosis by preventing the generation of ROS via the PI3K/AKT pathway." (PMID 35559246, 2022). "DOT1L and di-methylated H3K79 were highly expressed in renal tubular epithelial cells and myofibroblasts in UUO kidneys and in in vitro cultures of these two types of cells; pharmacological inhibition of DOT1L with EPZ5676, a highly selective inhibitor of DOT1L, significantly reduced renal fibrosis." (PMID 31866860, 2019). "However, the role of Dot1L in renal fibrosis remains controversial." (PMID 38929505, 2024). "Within an IRI model, EPZ004777, a DOT1L inhibitor, demonstrated the capacity to suppress PI3K/AKT-mediated reactive oxygen species (ROS) production, ultimately mitigating renal fibrosis." (PMID 38929505, 2024). "Although the role of DOT1L in most kidney diseases is not known currently, our recent studies demonstrated that DOT1L was critically involved in the pathogenesis of renal fibrosis in a murine model of UUO-induced chronic kidney disease." (PMID 31866860, 2019). "Recent study pointed that DOT1L had no benefit to proximal renal tubule, it promoted the EMT of proximal tubular epithelial cell, even facilitated the activation of renal fibroblast, contributing to renal fibrosis." (PMID 38172378, 2024).
triple-negative breast carcinoma (6 papers, 2015 to 2025). An invasive breast carcinoma which is negative for expression of estrogen receptor (ER), progesterone receptor (PR), and human epidermal growth factor receptor 2 (HER2). "Variants of DOT1L have been detected in triple-negative breast cancer." (PMID 36585729, 2022). "A specific H3K79 methyltransferase DOT1L increase the MTDH expression by increasing H3K79me3 levels on its promoter to promoting angiogenesis in triple-negative breast cancer." (PMID 38977630, 2024).
acute lymphoblastic leukemia (5 papers, 2019 to 2024). Leukemia with an acute onset, characterized by the presence of lymphoblasts in the bone marrow and the peripheral blood. "DOT1L is the only known histone 3 lysine 79 (H3K79) methyltransferase, while AML or acute lymphocytic leukemia (ALL) is a malignant clonal disease of hematopoietic stem cells, and without any special treatment, these patients can only survive for about 3 months." (PMID 34149432, 2021). "In KMT2A-rearranged acute lymphoblastic leukemia (ALL), an aggressive malignancy, oncogenic KMT2A-fusion proteins inappropriately recruit DOT1L to promote leukemogenesis, highlighting DOT1L as an attractive therapeutic target." (PMID 37740239, 2023).
dilated cardiomyopathy (5 papers, 2017 to 2024). Cardiomyopathy which is characterized by dilation and contractile dysfunction of the left and right ventricles. "DOT1L loss in cardiomyocytes leads to dilated cardiomyopathy due to the aberrant expression of genes essential for heart function." (PMID 38665093, 2024). "By contrast, H3K79me3 is added by the histone-lysine N-methyltransferase DOT1L, which is repressed during dilated cardiomyopathy." (PMID 34568453, 2021). "Consistently, DMD protein level is reduced in DOT1L-ablated hearts, which displays dilated cardiomyopathy." (PMID 34568453, 2021). "DOT1L-specific depletion in cardiomyocytes triggers the total depletion of H3K79me2/3 and finally the reduction of the dystrophin (DMD) gene, a membrane-associated protein involved in dilated cardiomyopathy and muscular dystrophy." (PMID 34568453, 2021).